RIPK3 (receptor interacting serine/threonine kinase 3)
Diseases named in the same sentence as RIPK3 in open-access papers (continued):
Sharing a sentence is not in itself a finding about the gene and the disease.
tumor (continued). "We found that the levels of ZBP1 and RIPK3 expression are dramatically elevated in necrotic tumors during tumor development." (PMID 33976222, 2021). "Another study also showed that a deficiency of receptor-interacting protein kinase 3 (RIPK3) in TAMs facilitated FAO and induced M2 polarization in the tumor microenvironment." (PMID 34638609, 2021). "Taken together, our data indicate that the activation of RIPK1/RIPK3 within the tumor microenvironment promotes the synthesis of immunostimulatory cytokines, thereby activating anti-tumor immunity." (PMID 34419074, 2021). "Taken together, our results support that tumor encounter modifies the TNF/RIPK3-dependent induction of caspase-8 activity to TNF/RIPK3-dependent caspase-1 activity after PH." (PMID 33178579, 2020). "In colon cancer, PGE2 derived through COX-2 has been shown to lead to a feed forward mechanism, in which receptor-interacting protein kinase 3 (RIPK3) results in activation of myeloid suppressor cells and suppression of anti-tumor immunity." (PMID 33364964, 2020). "We further evaluated the protein expressions of autophagy markers (ATG5, ATG7, Beclin-1, and LC3 B) and necroptosis markers (RIPK1, RIPK3) in NGP xenograft tumor tissues after rapamycin and MK-2206 combination treatment by Western Blot." (PMID 32116708, 2020). "While PH-induced KC disappearance was still abrogated in H+PH TNFM−KO mouse, we observed a sharp drop of KC in H+PH RIPK3 KO mice 2 days post PH, in opposition with KC survival in tumor-free RIPK3 KO mice after PH." (PMID 33178579, 2020). "Recently, it has been shown that oncolytic virus‐mediated induction of RIPK3 expression in tumor cells conferred durable tumor clearance and an abscopal effect." (PMID 33179413, 2020). "RIPK3 is a key regulator of necroptosis, which plays a double-edged sword role in tumor progression." (PMID 32521727, 2020). "The capability of RIPK3 to negatively regulate the activation of different signaling pathways, such as NF-κΒ, together with its antitumoral function identified RIPK3 as a tumor suppressor in CRC." (PMID 32231206, 2020). "Recent research has suggested that RIPK3 promotes anti-cancer immune response by regulating natural killer T cells, as RIPK3(−/−) mice show reduced natural killer T cell responses to metastatic tumor cells." (PMID 33665167, 2020). "The authors showed that RIPK3 loss induced tumorigenesis via upregulation of NF-κΒ, STAT3, AKT, and Wnt-β-catenin pathways activation, thus in turn leading to aberrant tumor cell proliferation, colon inflammation, immune cell infiltration and finally CRC." (PMID 32231206, 2020). "The tumor-suppressing activity of RIPK3 has been documented in CRC, and its overexpression significantly reduces the proliferation, migration and invasion of cancer cells in vitro." (PMID 33050394, 2020). "To further verify that necroptosis was involved in this cell death, we detected RIPK1 and RIPK3 expression levels in NGP xenograft tumor tissues by immunohistochemistry staining." (PMID 32116708, 2020). "It is therefore interesting to note that Gemcitabine, has been shown to increase RIPK1 and RIPK3 expression, thereby, potentially promoting tumour progression in PDAC patients, albeit unintentionally." (PMID 31416294, 2019). "Upregulated RIPK3 expression is a general phenomenon in tumor necrotic areas playing a critical role in tumor growth and metastasis." (PMID 31719524, 2019). "Several groups reported that RIPK3 expression is inhibited in many tumor cell lines and several types of cancer." (PMID 31922095, 2019). "This study provided a clear illustration of the tumour promoting activity of RIPK1/RIPK3-mediated inflammation via myeloid-dependent immune suppression." (PMID 31416294, 2019). "VEGF-A and FGF-b was also detected in supernatant of transmigration assays of either wild-type or Ripk3−/− ECs with monocytes and tumor cells after 20 h." (PMID 28151480, 2017).
tumor (continued). "To determine the potential for the hematopoietic or stromal compartment to have a role in the reduction in tumor nodules found in Ripk3−/− lungs, we performed bone marrow chimeric experiments." (PMID 28151480, 2017). "The ability of Ripk3−/− monocytes to enhance transmigration of tumor cells through a wild-type endothelial layer further suggests a defect in the Ripk3−/− ECs to respond to extracellular cues." (PMID 28151480, 2017). "Additional wild-type and Ripk3−/− mice were then injected tail vein with B16-F10 cells and 14 dpi, after blinding, the lungs were counted for tumor nodules." (PMID 28151480, 2017). "Expression of E1A and adenovirus structural proteins was assessed using quantitative immunohistochemistry (IHC) in control (HeLa LZRS) and RIPK3-expressing tumours following a single intratumoural injection of dl922-947." (PMID 29238045, 2017). "Only a slight decrease in the number of tumor nodules was seen in Mlkl−/− mice, whereas the reduction of tumor nodules was seen again in Ripk3−/− mice." (PMID 28151480, 2017). "Transmigration assays showed decreased ability of tumor cells to transmigrate through the vascular endothelial layer, which correlated with decreased permeability in the Ripk3−/− mice after tumor injection." (PMID 28151480, 2017). "We therefore assessed if pulmonary vascular permeability after tumor injection was affected in the Ripk3−/− mice using the Evans blue permeability assay." (PMID 28151480, 2017). "In a therapeutic experiment using the HeLa-RIPK3 D2 clone, RIPK3 expression significantly enhanced the activity of intratumoural dl922-947, with complete elimination of 3/6 HeLa-RIPK3 D2 tumours compared to 0/6 HeLa-LZRS tumours." (PMID 29238045, 2017). "In summary, our study shows the kinase activity of RIPK1 and RIPK3 has a physiological role in the tumor microenvironment, in particular tumor cell extravasation and remodeling by altering the downstream signaling pathways of permeability factors." (PMID 28151480, 2017). "After 12 h, the level of RIPK3 protein was approximately twofold higher, suggesting a potential role for RIPK3 in tumor formation in the lung." (PMID 28151480, 2017). "It appears only during stress such as wound healing or tumor challenge, does RIPK3 become required for the response to the additional stimuli." (PMID 28151480, 2017). "We sought to differentiate the role of RIPK3 or necroptosis in tumorigenesis versus the tumor microenvironment by utilizing syngeneic mouse tumor models." (PMID 28151480, 2017). "There was a 46% (±7.6%) decrease in tumor nodules in the RIPK3 null lungs compared with wild-type (P<0.01)." (PMID 28151480, 2017). "In comparison with wild-type mice reconstituted with Ripk3−/− bone marrow, there was a decreasing amount of tumor nodules in the Ripk3−/− mice reconstituted with wild-type (17.6%±23) or Ripk3−/− bone marrow (38.6%±22.6), respectively." (PMID 28151480, 2017). "Our study shows that RIPK3 exerts tumor suppressor functions by negatively regulating activation of NF-κB, STAT3 and AKT, thereby protecting from aberrant IEC proliferation and CRC development." (PMID 27344176, 2016). "In Ripk3−/− mice, pSTAT3 was strongly expressed in most epithelial cells, as well as in many stromal and tumor infiltrating cells, whereas in WT mice pSTAT3 was observed in few infiltrating cells." (PMID 27344176, 2016). "Our results further confirmed the important role of RIPK3 in maintaining in vivo tumor growth in the 4T1 model with RipK3 knockout 4T1 tumor cell growing at a significantly slower rate than vector control cells." (PMID 26959742, 2016). "Collectively, these results strongly suggest that RIPK3 plays a crucial role in the NKT cell-mediated anti-tumour immune response." (PMID 26381214, 2015). "Ripk3−/− mice show reduced NKT cell responses to metastatic tumour cells, and both deletion of RIPK3 and pharmacological inhibition of Drp1 protects mice from NKT cell-mediated induction of acute liver damage." (PMID 26381214, 2015).
tumor (continued). "Again both, IL-1α release and DC activation, were strictly dependent on RIPK3 expression in the tumor cells." (PMID 25888634, 2015). "H&E and RIPK3 staining showed a number of necrotic foci in tissue from RIPK3-overexpressing xenograft tumors, and this reduced the tumor size." (PMID 24959694, 2014). "After identifying aberrant methylation patterns of RIPK3 in OS primary tumor samples, quantitative real time PCR (qRT-PCR) analysis (HPRT was the normalizing control) found minimal to absent RIPK3 mRNA expression in the OS cell lines compared to the small intestine tissue control." (PMID 40332549, 2025). "Mice bearing MLKL-deficient or RIPK3-deficient tumors failed to control tumor growth in response to anti-PD-1/anti-CTLA-4 immunotherapy." (PMID 40345706, 2025). "In contrast, our approach with genetic deletion of Ripk3 or Mlkl in tumor cells suggests some extent of spontaneous and potentially continuous pro-necroptotic signaling in tumor cells as the ignition point of basal T-cell immunity and necessity for the success of subsequent ICI immunotherapy." (PMID 40345706, 2025). "Furthermore, Mn2+‐induced reactive oxygen species (ROS) amplify ferroptosis and, in conjunction with RIPK3‐mediated necroptosis, remodel the immunosuppressive tumor microenvironment by promoting M1 macrophage polarization and a Th1‐type immune response." (PMID 40755438, 2025). "Similarly, markedly elevated levels of RIPK3 methylation were identified in 6 of 11 primary OS tumor samples compared to normal bone and human osteoblasts." (PMID 40332549, 2025). "Dysregulation of RIPK3 has been frequently observed in tumor cells, including those from colorectal, breast, and lung cancers, contributing to impaired necroptotic signaling and enhanced tumor survival." (PMID 40900810, 2025). "This suggests that the combination treatment may have enhanced the TNFR1 signaling axis to activate the RIPK1/RIPK3 pathway, further driving necroptosis and promoting inflammatory responses within the tumor immune microenvironment." (PMID 41008944, 2025). "Ripk3 is a crucial gene in necroptosis by participating in cellular reactive oxygen species accumulation, promoting fatty acid oxidation and inducing the polarization of M2 macrophages in the tumor microenvironment." (PMID 40090940, 2025). "A further challenge is the development of drug resistance, as tumor cells may escape PCD via epigenetic silencing—such as RIPK3 promoter methylation—or metabolic reprogramming, including glycolysis-driven inhibition of necroptotic signaling." (PMID 41267084, 2025). "In contrast, the expression or activation state of PANoptosis regulators (e.g., ZBP1, RIPK3, and caspase-8) can be altered by factors such as hypoxia, metabolic stress, and DNA damage in the tumor microenvironment, potentially suppressing or reprogramming PANoptosome formation." (PMID 40422233, 2025). "RIPK3 may facilitate tumor proliferation in certain malignancies that are RIPK3-positive or overexpressing RIPK3." (PMID 40422233, 2025). "Concurrently, the generation of ROS by manganese, in conjunction with ferroptosis and RIPK3 expression‐induced necroptosis, further modifies the immunosuppressive tumor microenvironment, thereby promoting M1 macrophage polarization and favoring a Th1‐type immune response." (PMID 40755438, 2025). "Notably, in contexts of low expression RIPK3 activation, cells can sustain NF-κB-driven inflammatory responses without immediate lysis, contributing to chronic inflammation and tumor progression." (PMID 41354733, 2025). "Notably, RIPK1 and RIPK3 were highly expressed in normal tissues, suggesting their potential roles as tumor suppressors in KIRC progression." (PMID 40969770, 2025). "At tumor site, MUC1@ACS NPs released SK and Chi-Ag NPs in response to acidic environment, causing tumor cell necrosis by increasing expression levels of tetrameric MLKL, RIPK3, p-RIPK3, and, which subsequently triggered ICD." (PMID 40689201, 2025).
tumor (continued). "Necroptosis plays dual roles in cancer: it acts as a tumor suppressor in colorectal and hepatocellular carcinomas, where RIPK3/MLKL downregulation correlates with poor prognosis, but may promote inflammation-driven malignancy in specific contexts." (PMID 41235238, 2025). "Consistently, no endogenous expression could be detected in almost all cell lines, which we used for our subsequent functional analysis of RIPK3 tumor suppressive function." (PMID 38397165, 2024). "However, the mechanism by which PMN-MDSCs simultaneously up-regulate FATP2 and down-regulate RIPK3 mediated suppressive immunity in the tumor microenvironment is still unclear." (PMID 38461272, 2024). "Furthermore, the tumor-free mice survived until the termination of the experiment, confirming the effectiveness of the inducible RIPK3 safety switch in tumor cells in vivo." (PMID 39560995, 2024). "Importantly, we demonstrated that thimerosal can elevate intracellular ROS levels, thereby activating the RIPK3/IRF1/IRG1 axis to enhance tumor immunogenicity." (PMID 39349845, 2024). "Notably, RIPK3-dependent necroptosis activation downstream of RIPK1 contributes significantly to antileukemic activity, supporting the identification of RIPK3 as a tumor suppressor." (PMID 38730609, 2024). "Altogether, RIPK3-mediated necroptosis has significant effects on tumor growth, progression, and metastasis, indicating that targeting RIPK3-mediated necroptosis represents an effective strategy for inhibiting tumor development and progression in clinical practice." (PMID 38684668, 2024). "In line with this, tumor RIPK3 expression appears to aid tumor immune surveillance." (PMID 38858387, 2024). "Additionally, delivering the RIPK3 gene to tumour cells using an AAV vector induced necroptosis in melanoma cells." (PMID 38594879, 2024). "Furthermore, the RIPK3 system demonstrated the ability to stimulate prolonged antitumor immunity in mice, inhibit tumor growth, and enhance survival outcomes." (PMID 39560995, 2024). "Additionally, investigations highlight the activation of RIPK1/RIPK3 as a critical upstream target that facilitates the initiation of tumor immunity, indicating its potential therapeutic potential in cancer treatment strategies." (PMID 39209834, 2024). "RIPK3 is a necroptosis promoter; so, inhibiting RIPK3 may also facilitate HCC development by suppressing the necroptosis of tumor cells." (PMID 38786029, 2024). "Here, we utilized a system to drive RIPK3-dependent necroptosis or apoptosis without death-independent NF-κB activation to interrogate the impact of necroptosis-associated DAMPs release in tumor immunity." (PMID 38858387, 2024). "Additionally, compared to stage I/II patients, stage III/IV patients have high expression of FATP2 and low expression of RIPK3 in tumor tissues." (PMID 38461272, 2024). "In addition, RIPK3 can promote the anti-tumor immune effects of CD8+ T cells by mediating necroptosis." (PMID 38684668, 2024). "Additionally, methylation near the transcription start site can silence RIPK3 expression in tumour cells." (PMID 38594879, 2024). "In addition, RIPK1 and RIPK3 are strongly correlated with high levels of tumour migration and metastasis in pancreatic cancer." (PMID 38652105, 2024). "Generation of engineered tumor cells with an inducible RIPK3-driven necroptotic safety switch." (PMID 39560995, 2024). "RIPK3 can promote tumor growth in some RIPK3-positive or -overexpressing cancers." (PMID 38684668, 2024). "Intracellular ROS may activate RIPK3 in tumor cells, and thimerosal is known to induce ROS in tumor cells." (PMID 39349845, 2024). "Moreover, RIPK3 can induce anti-cancer immune surveillance mediated by T cells to limit tumor progression and limit tumor development by inducing and facilitating the secretion of cytokines and chemokines." (PMID 38684668, 2024). "In addition, reestablishing endogenous RIPK3 expression resulted in reestablishing its tumor-suppressive function." (PMID 38397165, 2024).
tumor (continued). "Findings of recent years indicate that RIPK3 is a tumor suppressor gene." (PMID 38397165, 2024). "Tumor cell death induced by the RIPK3 safety switch elicits long-term immunity in vivo." (PMID 39560995, 2024). "The ability of the RIPK3-driven safety switch to induce long-term immunity, as evidenced by our findings, marks a meaningful stride in cancer immunotherapy, especially in the context of tumor recurrence prevention." (PMID 39560995, 2024). "To explore the impact of overexpressing Ripk3 or Mlkl on the potential progression of cancer at 5, 8, and 14 months in the mice, we measured the mRNA levels of three genes, which play a role in the regulation of tumor development and increase in the array." (PMID 39514172, 2024). "Additionally, RIPK3-mediated anti-tumor immune responses have been reported to involve natural killer T (NKT) cells." (PMID 38546403, 2024). "In the context of this review, it is worth noting that the tolerogenic phenotype exhibited by tumor-associated macrophages in PDA was reliant on RIPK1 but independent of RIPK3 and necroptosis." (PMID 38576612, 2024). "Indeed, ADAR1 inhibits ZBP1-mediated activation of NLPR3 inflammatory vesicles and cell death by competitively binding to ZBP1 with RIPK3, ultimately leading to tumor development." (PMID 37771585, 2023). "RIPK3 expression is frequently inhibited in tumor cells through promoter hypermethylation." (PMID 38196632, 2023). "Another study confirmed that RIPK1 and RIPK3 may be highly expressed in tumor-reactive T cells and undergo necrosis upon restimulation of the T cell receptor (TCR) with cognate antigen, which can be inhibited via RIPK1 inhibition." (PMID 37061535, 2023). "RIPK3 then phosphorylates mixed lineage kinase domain-like (MLKL), leading to plasma membrane disruption and release of DAMPs (damage-associated molecular patterns) and tumor antigens." (PMID 37513508, 2023). "In HCC cells with intrinsic RIPK3 deficiency, knockout of MLKL impedes the orthotopic tumor growth, activates the anti-tumor immune response and enhances the therapeutic effect of immune checkpoint blockade in syngeneic HCC tumor models." (PMID 36650126, 2023). "For instance, IRF1 functions in both myeloid and epithelial cells to counteract AOM/DSS-induced colorectal tumorigenesis, while RIPK3 activation in colon cancer cells leads to increased cytokine expression in the tumor microenvironment, contributing to robust cytotoxic anti-tumor immunity." (PMID 37398672, 2023). "Consequently, there remains a need to clarify the consequences of these distinct aspects of tumor RIPK3 signaling in the antitumor response." (PMID 38196632, 2023). "In contrast, tumor RIPK3 expression appears to be beneficial for tumor immune surveillance." (PMID 38196632, 2023). "Höckendorf and colleagues identified RIPK3 as a key tumor suppressor in AML." (PMID 37993258, 2023). "ZBP1 and RIPK3 also play important roles in tumor development." (PMID 37501725, 2023). "Additionally, when combined with a Smac mimetic LCL-161, an IAP antagonist, quercetin or kaempferol synergistically induced RIPK1/RIPK3/MLKL-mediated necroptosis in CCA cells while sparing non-tumor cholangiocyte cells." (PMID 37513508, 2023). "However, after knocking out the RIPK3 gene in mice, the number and size of tumors were significantly reduced, and the tumor load was also reduced." (PMID 35963853, 2022). "For instance, RIPK3 activation-triggered de-inhibition of tripartite motif protein 28 (TRIM28) in tumor cells results in increased immunostimulatory cytokine production within the tumor microenvironment and thus contributes to robust cytotoxic antitumor immunity." (PMID 35662734, 2022). "Inhibition the signal pathway by silence RIPK3 or suppresses the activity of RIPK3 may abolish inflammatory responses which is critical in modulating tumor initiation and progression." (PMID 35957699, 2022).